APP (amyloid beta precursor protein)
Diseases named in the same sentence as APP in open-access papers (continued):
Sharing a sentence is not in itself a finding about the gene and the disease.
amyloid (continued). "The gene for APP encodes a full-length APP protein (fl-APP) and its products, including transmembrane C-terminal fragments (CTFs) as well as the Aβ peptides that accumulate in amyloid plaques and whose presence in toxic oligomeric species is viewed as an essential contributor to pathogenesis." (PMID 33691783, 2021). "When combined with results from the in vitro study by Liu and colleagues, our in vivo results suggest one mechanism by which STAT3 inhibition attenuates amyloid pathogenesis and its associated neurovascular deficits is by attenuating APP processing through inhibition of BACE1 activity." (PMID 34911575, 2021). "According to this hypothesis, the cause of AD is formation and accumulation of amyloid plaques from fragments of the Aβ amyloid precursor protein (APP), which cause a cascade of molecular events, leading to loss of cell function and their death." (PMID 34062910, 2021). "Quantitative analysis of amyloid-associated astrocyte processes and body area revealed that 9-cis RA treatment dramatically reduced the level of reactive astrocytes associated with Aβ-positive plaques in the brains of 7-month-old APP/PS1 mice." (PMID 32209731, 2020). "Finally, multiple mutations in the APP gene that increase misfolding and aggregation can predispose individuals to develop hereditary cerebral hemorrhage with amyloidosis (HCHWA), a heritable form of CAA that is associated with early and severe disease onset." (PMID 33329053, 2020). "We investigated whether a mutated humanized mouse APP gene, driven by the endogenous mouse promoter, is sufficient to induce typical amyloidosis and DN formation in mice." (PMID 32469963, 2020). "To examine whether the reduced amyloidosis in the presence of ECH was caused by the reduction in APP metabolism through BACE1, we next examined the effect of ECH on the secretion of sAPPβ by Western blot." (PMID 33330477, 2020). "In animal models, TNFR1 is associated with amyloidosis and APP processing." (PMID 31555121, 2019). "Some proinflammatory cytokines, such as IL-1β and IL-6, have been associated with reduced amyloidosis and amelioration of cognitive deficits in APP mouse models, and may contribute to the beneficial effects of FUS in AD." (PMID 30232364, 2018). "Studies of early-onset forms of familial AD, Down syndrome, and transgenic rodent models that overexpress normal or mutated forms of the amyloid precursor protein (APP) suggest formation of amyloid plaques may play a key role in the disease." (PMID 30192871, 2018). "5XFAD;BACE1−/− mice, which overexpress APP and PS1 transgenes but do not generate Aβ, allowed us to determine if changes in ER stress occurred, and if so, whether they were caused by amyloid pathology or by prolonged overexpression of APP and PS1." (PMID 30315100, 2018). "Furthermore, increased levels of APP can also be linked to amyloidosis in Down syndrome (DS), since the APP gene is located on chromosome 21, which is triplicated in DS." (PMID 29061112, 2017). "However, a more physiological murine model of inherited AD with slow developing amyloidosis was generated by targeted mutations in humanised APP (KM670/671NL) and PS1 (P264L)." (PMID 28637503, 2017). "This is in contrast to overproduction which leads to amyloid accumulation from mutations affecting APP processing (e.g., mutations in APP or presenilin complex), resulting in early-onset Autosomal Dominant AD or trisomy 21, which predisposes to early-onset dementia in Down’s syndrome." (PMID 25999850, 2015). "Given the reports of cognitive deficits in mice that express mutant APP and the association, in some cases, of these deficits with amyloid deposition, we sought to determine whether the BRI2-Aβ1-42 mice manifest detectable cognitive deficits." (PMID 23663320, 2013).
amyloid (continued). "The finding that besides its overexpression APP must be also mutated for the production of high levels of Aβ led later to generation of new animal models; these mice developed age-dependent AD-like pathology including amyloid deposit in brain parenchyma." (PMID 23801962, 2013). "To examine whether the reduced amyloidosis in the presence of thalidomide may be caused by a reduction in APP metabolism, we at first observed the secretion levels of sAPPβ fragments by Western blot." (PMID 23405115, 2013). "Elevated BACE1 and APP levels in plaque-associated presynaptic dystrophies could increase local peri-plaque Aβ generation and accelerate amyloid plaque growth in AD." (PMID 23820808, 2013). "The transgenic Swedish Dutch Iowa (Tg-SwDI) mouse model is an amyloidosis model expressing low levels of the human amyloid-β precursor protein (APP) gene with three familial mutations, of which the Dutch and Iowa mutations are located in the amyloid-β coding region of APP." (PMID 33577447, 2021). "This new class of APP translation inhibitors may, in fact, be considered most suitable to treat the orphan disease of APP-trisomy that causes the Dup–APP (hemorrhagic AD) as a form of fAD and also for cases of amyloidosis with complications in DS patients over 40 years of age." (PMID 30823541, 2019). "Hereditary cerebral hemorrhage with amyloidosis-Dutch type (HCHWA-D) is an early onset hereditary form of cerebral amyloid angiopathy (CAA) caused by a point mutation resulting in an amino acid change (NP_000475.1:p.Glu693Gln) in the amyloid precursor protein (APP)." (PMID 29706885, 2018). "Thus, the mechanism underlying amelioration of amyloidosis in our choline supplemented APP.PS1 mice may be potentially mediated by reduced activity of γ-secretase." (PMID 28103298, 2017). "In support of reduced vulnerability to amyloidosis-associated neurotoxicity, subchronic (3 weeks) exendin-4 treatment has been shown to reduce soluble β-amyloid levels, to lower cortical amyloid plaque load and improve memory performance in a double transgenic APP/PS1 mouse model of amyloidosis." (PMID 27421117, 2016). "In addition, the mouse models used to study the effects of TREM2 on amyloid plaque clearance not only highly overexpress APP but also express rather aggressive familial AD‐associated mutations, which may override modulatory effects of TREM2." (PMID 27402340, 2016). "APP and its pathogenic cleavage product, β-amyloid, physically and functionally interact with ApoE receptors on multiple levels, by regulating the trafficking and processing of APP, mediating amyloid clearance and by preventing amyloid-induced synaptic suppression at the synapse." (PMID 23986861, 2013). "Although the mechanism of GSK3 modulation in the AD brain is far from completely understood, it is reasonable to speculate that the regulation of insulin deficiency in APP processing to the amyloidosis pathway is, at least partly, through activation of GSK3 signaling." (PMID 21044348, 2010). "Consistent with our data, a study in APP/PS1 mice - a mouse model for studying amyloid pathology - indicated a disruption in CDH5 expression that occurred before plaque formation and BBB breakdown." (PMID 41566484, 2026). "This highlights that males were more motivated by water‐seeking behavior than females and is consistent with motivational sex differences we had previously observed in the APP/PS1 mouse model of amyloidosis." (PMID 41457719, 2026). "We investigated this cerebellar resistance using 5xFAD mice, an amyloidosis model with high expression of mutant human APP and PSEN1 in the cortex and cerebellum." (PMID 41597256, 2026). "Here, we examined how iTBS affects cortical synapses in the adult APP/PS1 amyloidosis mouse model of AD, compared with their wild-type counterparts." (PMID 40438149, 2025). "Thioflavin‐S staining was used to observe the changes in amyloid plaques in the brains of APP/PS1 mice." (PMID 40047153, 2025).
amyloid (continued). "Deletion of Ptk2b in APP/PS1 transgenic mice rescued synaptic loss and memory deficits, whereas overexpression rescued behavior and increased amyloid plaque number in 5xFAD mice." (PMID 40026671, 2025). "APP is another critical protein in AD, and its phosphorylation plays a significant role in the generation of Aβ peptides, the primary components of amyloid plaques." (PMID 40449795, 2025). "AD-associated risk genes, including APP, PICALM, and RBFOX1, were positively correlated with plasma cells, activated CD4+ T cells, and Tregs, linking amyloid-related pathways to adaptive immune activation." (PMID 41567547, 2025). "Amyloid plaques primarily comprises of 36-43 amino acids long amyloid peptides (Aβ), which forms as a results of the proteolytic cleavage of amyloid precursor protein (APP)." (PMID 40479573, 2025). "Other APP mutations that give rise to familial CAA include the Icelandic, British, Danish, and Familial amyloidosis-Finnish mutations." (PMID 41035821, 2025). "When the amyloidosis pathway of APP is upregulated, it eventually leads to increased Aβ production and promotes the onset of AD." (PMID 41409784, 2025). "The reduction in amyloid plaque density, mitigated neuroinflammation, and decreased astrogliosis observed in NC-treated APP/PS1 mice likely underpins the observed behavioral improvements." (PMID 40801602, 2025). "It was also shown that changes in the levels of Beclin1 in APP transgenic mice affect extracellular amyloid pathology." (PMID 41123674, 2025). "According to the 2024 Nomenclature meeting of the International Symposium for Amyloidosis, the terms APP and plaques, used to describe the amyloid aggregates that are associated with AD, are technically incorrect." (PMID 41035821, 2025). "Here, we found reduced cortical Aβ levels and a smaller area of dystrophic neurites around amyloid plaques in relation to amyloid plaque area in APP/PS1/Hif-p4h-2gt/gt mice." (PMID 40609789, 2025). "Both N-glycosylation and O-glycosylation play critical roles in the modulation of key proteins such as APP and tau, with direct implications for amyloid plaque formation and neurofibrillary tangle development." (PMID 40449795, 2025). "Amyloid plaques consist of Aβ protein derived from an origin protein called the amyloid precursor protein (APP), which has four parts—α, β, γ, and η—that create three pathways." (PMID 40143166, 2025). "More recently, iTBS was found to attenuate cognitive decline and amyloid pathology development and preserve mitochondrial function in APP/PS1 mice." (PMID 40438149, 2025). "5xFAD mice express 5 familial AD mutations resulting in overexpression of APP and PSEN1 and exhibit early onset amyloid pathology and cognitive deficits." (PMID 39919123, 2025). "For instance, administration of B. fragilis resulted in an increased amyloid plaque burden in the cortex of APP/PS1 mice." (PMID 40423637, 2025). "For example, in a recent study, a CCK analog effectively improved spatial learning and memory, reduced amyloid plaque load in the brain, enhanced synaptic plasticity in the hippocampus, and normalized synapse number and morphology in APP/PS1 mice." (PMID 40013092, 2025). "The histological examination was performed to assess the effect of Semax andHeptapeptide on the development of amyloidosis in APP/PS1 mice." (PMID 41479572, 2025). "Aβ1-42, dysregulated amyloidogenic pathway in amyloid precursor protein (APP) processing, is thought to be the key component of amyloid plaques and is shown to be neurotoxic in AD pathogenesis." (PMID 40357234, 2025). "The APP/PS1 double-transgenic mice, carrying human APP (Swedish mutation) and PS1 (exon 9 deletion), are a widely used AD model that develops early amyloid plaque deposition, along with gliosis, synaptic dysfunction, and progressive cognitive deficits." (PMID 41516046, 2025).
amyloid (continued). "In this study, KBN2202 reduced APP-CTFs in the hippocampus at the molecular level and attenuated amyloid plaque deposition in both the cortex and hippocampus." (PMID 41303432, 2025). "When injected into animal models, Aβ-containing homogenates from AD or APP transgenic mouse brain accelerate amyloid pathology, but the nature of the seeding species remain ill-defined." (PMID 40410917, 2025). "These mutations disrupt amyloid precursor protein (APP) processing, leading to abnormal cleavage by β- and γ-secretases and subsequent amyloid plaque formation, a hallmark of AD." (PMID 40004464, 2025). "In order to test the hallmark, progressive, cognitive impairments observed in amyloid diseases, and other amyloid mouse models, we examined both APP KI genotypes across a battery of behavioral tests through aging." (PMID 39920176, 2025). "In the present study, chronic exposure of aged, humanized APP-KI mice to dim light at night (8 lux during the dark phase) disrupted circadian activity rhythms and altered neuropathological outcomes in an amyloid-prone background." (PMID 41256678, 2025). "In the APP/PS1 mouse model of amyloidosis, Xue and colleagues reported that neuronal knockout of CD2AP exacerbates tau hyperphosphorylation, synaptic impairments and cognitive deficits." (PMID 40462155, 2025). "At 9 months, corresponding to early amyloid pathology, leptin levels were elevated in the hippocampus of APP/PS1 mice but unchanged in the neocortex." (PMID 41516046, 2025). "While total APP expression (human and murine) was significantly reduced in 5xFADXTg30XAPP-/- mice due to the deletion of murine APP, amyloid pathology was notably increased in the hippocampus of these mice compared to 5xFADXTg30 controls." (PMID 40001463, 2025). "The high risk for DSAD is due to an overproduction of amyloid‐beta (hereon referred to as amyloid), driven by the triplication of the amyloid precursor protein (APP) located on chromosome 21." (PMID 40799171, 2025). "Here, we investigated the effects of long-term chronic anti-Aβ treatment on amyloid plaque pathology and microglial response in the APP-SAA triple knock-in mouse model with an intervention paradigm early during amyloidogenesis." (PMID 40830489, 2025). "Low-dose IL-2 treatment in the mid-stages of AD restores the Treg/Th17 balance, reduces neuroinflammation, and decreases amyloid plaque burden in APP/PS1 (Amyloid Precursor Protein/Presenilin-1) models, significantly improving cognition." (PMID 41357230, 2025). "We show that systemic HIF-P4H-2 deficiency, which activates the HIF pathway in normoxia, results in healthier metabolism and lesser amyloid load and toxicity in APP/PS1 mice." (PMID 40609789, 2025). "AppNL−F/NL−F mice are knock-in mice which express partially humanized APP within the endogenous murine APP locus and evince an age-dependent accumulation of amyloid and deterioration in the performance of various learned behaviors." (PMID 40410917, 2025). "GM3 was previously found to be increased with amyloid pathology in APP-SAA KI mice and is enriched in microglia that have phagocytosed MX-04+ Aβ." (PMID 40830489, 2025). "APP and APP/PS1 mice are commonly used amyloidosis models due to their rapid Aβ plaque accumulation, though they lack significant neurodegeneration and tau pathology." (PMID 40143845, 2025). "Similar to P301S mice, APP/PS1 mice exhibit well-characterized synaptic deficits due to amyloid accumulation, making them a suitable model for studying synaptic pathology and its potential reversal." (PMID 40691577, 2025). "Consistent with previous studies in APP models, in our study, the AD brain inoculum was able to induce amyloid pathology in 3xTg‐AD mice; specifically, both diffuse and neuritic plaques formation was accelerated." (PMID 40364523, 2025). "Diminished vascular reactivity in APP/PS1 mice was associated with increased cerebral amyloid angiopathy and amyloid-plaque burden." (PMID 41394343, 2025).
amyloid (continued). "Laser microdissection of amyloid plaque-containing regions from AD brain sections, controls, and APP/PS1 transgenic mice." (PMID 41008617, 2025). "In sum, our analysis of the APP NL-F mouse model revealed that epichaperome formation begins in the early, preclinical stages of AD, well before the onset of amyloid plaque formation and cognitive decline." (PMID 39989971, 2025). "Two models of amyloidosis (5xFAD and APP/PS1) and one of tau pathology (PS19) were investigated (age = 42.5 ± 6.5 weeks)." (PMID 41235867, 2025). "To investigate vascular amyloid pathology in the APP-SAA KI mouse, we used HS169, a compound that binds to both diffuse and fibrillar plaques and vascular Aβ deposits." (PMID 40830489, 2025). "LDC alcohol feeding to Tg2576 mice caused mild liver injury, and important amyloidosis-relevant hepatic proteins (LRP-1 and APP) were largely unaltered." (PMID 40196176, 2025). "To test this, we recorded from large neuronal populations in dorsal CA1 (dCA1) and ventral CA1 (vCA1), two hippocampal areas known to be structurally and functionally diverse, in the APP/PS1 mouse model of amyloidosis." (PMID 38709845, 2024). "BACE-1 is a critical enzyme in the amyloidogenic pathway, responsible for the cleavage of amyloid precursor protein (APP) and the subsequent formation of β-amyloid peptides, which aggregate to form amyloid plaques in AD." (PMID 39598743, 2024). "Overall, our data show that male and female APP/PS1 mice present with vascular dysfunction that occurs prior to the onset of amyloid pathology." (PMID 38862757, 2024). "Previous studies using brain extracts from AD human patients or APP-transgenic mice accelerated progression and severity of amyloid aggregation and deposit in various APP transgenic models such as Tg2576." (PMID 38462606, 2024). "APP and PSEN1 mutant gene overexpression caused ADLPAPP/PS1 mice to develop more aggressive amyloidosis than AppNL-G-F mice." (PMID 39218977, 2024). "The relatively modest synapse gain and loss across CA1 dendritic compartments from Tg2576 mice in comparison to age-matched APP/PS1 mice is consistent with its slower progression of amyloid pathology." (PMID 39262788, 2024). "It is a reticulon protein, which plays a role in blocking BACE1 access to APP, thereby reducing Aβ production and potentially limiting amyloid plaque formation." (PMID 39535480, 2024). "Previous studies have found increased numbers of CD8 + T cells in the postmortem brain tissue of patients with AD, which was also validated in a murine APP/PS1 amyloidosis model." (PMID 39610716, 2024). "In the APP/PS1 mouse model of amyloidosis, treatment with MW150 prevented the development of memory deficits without affecting amyloid plaque accumulation." (PMID 39339348, 2024). "Our findings revealed that the early upregulation of A2AR in the presence of an ongoing amyloid pathology exacerbates memory impairments of APP/PS1 mice." (PMID 38964748, 2024). "Beta-amyloid arises from the sequential cleavage of the amyloid precursor protein (APP) by two proteases, beta- and gamma-secretase." (PMID 38285515, 2024). "The findings revealed that ultrasound stimulation influenced microglial polarization and alleviated amyloid pathology in APP/PS1 mice." (PMID 39588954, 2024). "Since AMPAR removal most likely mediates synaptic loss in amyloidosis AD models, we assessed AMPAR trafficking in APP/PS1 neurons." (PMID 38915938, 2024). "TRPV1 activation through chronic dietary capsaicin decreases amyloid pathology and attenuates cognitive deficits in APP/PS1 mice." (PMID 39468688, 2024). "We used male and female mice prior to the onset of amyloid pathology (3 months old; referred to as 3-month-old APP/PS1 mice) or during the onset of amyloid pathology (7 months old; referred to as 7-month-old APP/PS1 mice)." (PMID 38862757, 2024). "Our results demonstrate that Aβ/APP-products drive broad and input-specific synapse reorganization during early stages of amyloidosis." (PMID 39262788, 2024).